MTOR (mechanistic target of rapamycin kinase)
Diseases named in the same sentence as MTOR in open-access papers (continued):
Sharing a sentence is not in itself a finding about the gene and the disease.
cancer (continued). "AMPK and mTOR are the key regulators of cellular energy in cancers." (PMID 36293209, 2022). "Gene mutations in PIK3CA, PIK3R1, and PTEN are commonly detected in type I EC and may lead to activation of the PI3K/Akt/mTOR pathway, which is central to cell growth and proliferation in cancer." (PMID 35902869, 2022). "In this study, it was found through experiments that the LNM of LSCC cells is linked to the overexpression of PI3K axis-related proteins in cancer tissues, and inhibiting the PI3K/Akt/mTOR axis activity may help reduce the risk of LNM in LSCC patients." (PMID 36052284, 2022). "Indeed, mTOR inhibitors were approved for the treatment of human cancers including advanced neuroendocrine tumors and advanced breast cancer." (PMID 35372044, 2022). "Both cancer cells and MDSCs use mTOR signaling to modulate MDSC recruitment in TME." (PMID 36428613, 2022). "Additionally, activated mTOR signaling, as indicated by phospho-mTOR-S2448 levels in patients’ tumors predicts better clinical survival among multiple cancer types." (PMID 36396656, 2022). "Inhibitors of mTOR are therefore considered a valuable addition to chemotherapy or targeted cancer therapy, either as an option for relapsed patients or as a frontline combination therapy to prevent or delay the development of resistance due to sustained mTOR signaling." (PMID 36499000, 2022). "mTOR is considered to serve as a master regulator of this signaling pathway, and recent findings have reported that mTOR activation plays a vital role in human cancer." (PMID 35883111, 2022). "PD-1 blocking combined with targeting mTOR pathway may enhance the antitumor curative effect in cancer." (PMID 35069936, 2022). "The top 22 significantly cancer-associated terms of the GSEA were identified, including oxidative phosphorylation, MYC target, the mTORC1 signaling, E2F target, metabolism-associated pathway, DNA repair, PI3K/AKT/mTOR signaling." (PMID 36209249, 2022). "mTOR inhibitors had been widely used in cancer therapies for a long time." (PMID 36497433, 2022). "Furthermore, BCAAs were recently identified as an upstream signal input of the mTOR signaling pathway, which activates the pathway regulating the growth and proliferation of cancer cells." (PMID 35461343, 2022). "Finally, in vitro studies demonstrated that GOLPH3 regulates cell size, enhances growth factor-induced mTOR signaling in human cancer cells and modulates the response to rapamycin." (PMID 36387263, 2022). "The PI3K/mTOR pathway is a prime target for new cancer therapies." (PMID 35484114, 2022). "In recent years, studies have revealed that inhibiting the PI3K/Akt/mTOR signaling pathway can induce autophagic cell death by up-regulating the level of autophagy, which is an effective means to end or inhibit the progression of cancer." (PMID 36712689, 2022). "Moreover, preclinical approaches identified the mTOR/HDAC inhibitor combination as a promising strategy for cancer treatment." (PMID 35057104, 2022). "Currently, the FDA has approved mTOR inhibitors in the management of several cancers." (PMID 35216092, 2022). "Increased activation of the phosphatidylinositol-3-kinase (PI3K)/AKT/mTOR pathway results in many cancer hallmarks such as acquired growth signal autonomy, apoptosis inhibition, sustained angiogenesis, increased tissue invasion, metastasis, and anti-growth signal insensitivity." (PMID 35634241, 2022). "The pan-cancer analysis showed that MTOR mRNA is overexpressed in many cancers." (PMID 35883111, 2022). "Given that we observed few, if any, effects of HIF2A on translation, our results suggest that the combined use of these HIF2A transcriptional inhibitors, together with mTOR inhibitors, should therefore be considered as a rational therapeutic strategy for this type of cancer." (PMID 36097292, 2022).
cancer (continued). "In addition, we also detected the protein expression levels of the AMPK/mTOR signaling pathway in xenograft tumor tissues and clinical tumor tissues, and the results were consistent with previous results in cancer cells." (PMID 36293209, 2022). "Deregulated MTOR signaling is found in a variety of cancer subtypes." (PMID 35794338, 2022). "PI3K/AKT/mTOR inhibitors affect the PD-L1 expression in cancer cells." (PMID 36313041, 2022). "This interaction inhibits mTOR function and hinders cancer proliferation." (PMID 35327484, 2022). "mTOR plays a pivotal role in sustaining the growth and survival of cancer cells." (PMID 35955931, 2022). "According to several studies, Akt/mTOR activation occurs in OLP and may increase the risk of developing cancer." (PMID 36072973, 2022). "The mTOR signaling pathway plays an important role in cancer." (PMID 35883111, 2022). "Dysregulation of the PI3K/AKT/mTOR signaling pathway, which contributes to various biological processes, such as apoptosis, metabolism, cell proliferation, and cell growth, frequently occurs in cancer." (PMID 35203530, 2022). "Studies have been reported that oxamate could induce autophagy via downregulation HIF-1α through inhibiting the Akt-mTOR signaling pathway in cancer cells." (PMID 35370938, 2022). "In addition, AMPK activation can dramatically affect many cellular processes relevant to carcinogenesis and cancer progression, such as mTOR signaling and inflammation." (PMID 35807850, 2022). "Inhibition of mTOR—a SASP regulatory factor—leads to senolysis of senescent cancer cells." (PMID 36232388, 2022). "Indeed, many mTOR inhibitors have been approved to treat human cancer, while more mTOR inhibitors are being evaluated in clinical trials." (PMID 35655775, 2022). "However, rapamycin (mTOR inhibitor) disrupts also the senescence surveillance and paracrine senescence—two significant factors in cancer suppression, which show once again the duality of SASP effects on tumor growth." (PMID 36232388, 2022). "However, mice still succumb to further tumor progression due to cytostatic responses to mTOR inhibitors, which allows cancer cells to recover and continue their aggressive growth." (PMID 35484114, 2022). "While targeting The AKT/mTOR pathway could serve as promising strategies for cancer treatment, the efficacy of monotherapy with AKT inhibitors is limited." (PMID 35250566, 2022). "PGAM1 knockdown suppresses glycolysis and cancer genesis due to oncogenic mTOR signaling." (PMID 35674458, 2022). "AKT/mTOR signaling pathway is hyper-active in various cancers, including LUAD." (PMID 35773623, 2022). "Thus, the multifaceted effects of FC101 on mTOR/MAPK in TNBC warrant further investigation of its potential for a synergistic anti-cancer drug response." (PMID 36428475, 2022). "Related research reports that CKAP2L could activate the AKT/mTOR signaling pathway in cancer cells and promotes carcinogenesis." (PMID 36090903, 2022). "In addition to mTOR inhibitors, other autophagy-inducing drugs have been identified to treat cancer." (PMID 35831271, 2022). "In addition, the CCL2/CCR2 axis can promote cell survival by inhibiting autophagic death and apoptosis of cancer cells by activating the phosphatidylinositol 3-kinase (PI3K)/AKT/mammalian target of rapamycin (mTOR)-dependent pathway." (PMID 35281057, 2022). "The PI3K/AKT/mTOR pathway is crucial for cell motility, growth, survival, and metabolism in cancer." (PMID 35402264, 2022). "PI3K/Akt/mTOR, an important pathway for regulating cell growth in cells, affects the proliferation of cancer cells in breast, ovarian, and bladder cancer and other malignant tumors." (PMID 36052284, 2022).
cancer (continued). "Activation of PI3K/Akt/mTOR signaling pathway induces transcription of the sterol regulatory element-binding proteins (SREBPs), which subsequently promotes cholesterol uptake and synthesis to meet the demand of cancer cells." (PMID 35251975, 2022). "Increasing attention has been paid to the mTOR pathway specially because it could be a potential target for cancer therapy in both dogs and humans." (PMID 35883491, 2022). "Several mTOR inhibitors have been approved to treat human cancer." (PMID 36221123, 2022). "LARP1 can also regulate mTOR signaling to contribute to cancer progression." (PMID 35785179, 2022). "Drugs, such as buparlisib, everolimus, and perifosine, which target the PI3K/Akt/mTOR pathway, have the potential to inhibit survival pathways and induce apoptosis and autophagy in cancer cells, and they have been found to have favorable antitumor efficacies in clinical trials." (PMID 35280512, 2022). "PI3K/AKT/mTOR shows crosstalk with oxidative stress and DNA damage response in cancer cells." (PMID 36139919, 2022). "We used GSCALite to analyse the function of CXC chemokines of PDAC in the famous cancer-related pathways (the TSC/mTOR, RTK, RAS/MAPK, PI3K/AKT, hormone ER, hormone AR, epithelial–mesenchymal transition (EMT), DNA damage response, cell cycle, and apoptosis pathways)." (PMID 35468838, 2022). "mTOR pathway is known to promote cancer malignancy and influence cancer immunity but is unknown for its role in immune checkpoint inhibitors (ICI) therapy." (PMID 35642038, 2022). "Since mTOR inhibitors may enhance the PI3K/PDK1 axis, an inhibitor targeting both PI3K and mTOR may have better anti-cancer activity." (PMID 36010585, 2022). "On the other hand, it has been demonstrated mechanistically that when mTOR levels rise in cancer cells, it binds to MondoA directly in the cytoplasm and prevents the formation of the MondoA/Mlx complex which limits MondoA nuclear entry and TXNIP transcription and expression." (PMID 36366411, 2022). "Multiple studies have reported that the mTOR pathway may contribute to cancer stemness maintenance, chemoresistance and tumour development." (PMID 36056355, 2022). "Aberrant regulation or activation of the PI3K/Akt/mTOR cascade is mainly involved in the development of various human cancers such as acute lymphoma (AML), T cell acute lymphoblastic leukemia (T-ALL), breast cancer, ovarian cancer, prostate cancer, and mantle cell lymphoma." (PMID 35883653, 2022). "mTOR signaling pathway uses this metabolic activity to generate ATP and enhance cancer progression." (PMID 35327484, 2022). "Consistent with the previous reports that demonstrated apigenin’s anti-cancer and chemopreventive effects at cellular and molecular levels, particularly inhibition of the PI3K/AKT/mTOR signaling pathways, the report demonstrated targeting of the PI3K/AKT/mTOR axis by apigenin for cancer prevention." (PMID 35406599, 2022). "The activation of mTOR signaling is dependent on growth factors and nutrients in cancer cells." (PMID 35663990, 2022). "Despite potential toxicological challenges as ribosome biogenesis is also an important physiological process, modulation of NOP56 activity may afford a therapeutic window for targeted inhibition of mTOR in KRAS-mutant cancers." (PMID 35039048, 2022). "Previous researchers found that activating mTOR promoted the invasion and metastasis of cancer." (PMID 35449152, 2022). "Pathway enrichment results did not clearly indicate the nature of the association of TAARs with identified biological processes, and the results were insufficient to determine if TAAR6 was implicated in cancer-associated pathways, or TAAR6 only co-regulates with mTOR signaling in tumors." (PMID 35053262, 2022). "We performed supernatant transfer experiments and asked whether cancer patients EV stimulate AKT/mTOR in A549 cells either directly or via immune cells." (PMID 35461372, 2022).
cancer (continued). "The PI3K/AKT/mTOR pathway has emerged as one of the most frequently altered in human cancer." (PMID 35140788, 2022). "The recent literature suggests that the potential inhibition of mTOR activity may prevent cancer progression and improve the survival prognosis for patients after treatment." (PMID 35681658, 2022). "In cancer, the PI3K/mTOR pathway is almost universally activated by mutations." (PMID 35533376, 2022). "Though MeSG is known to negatively regulate PI3K/AKT/mTOR signaling pathway, the efficacy of MeSG could be limited due to drug resistance, especially in PTEN-deficient cancer cells." (PMID 36146655, 2022). "In conclusion, mTOR pathway activation leads to less cancer stemness and may serve as a therapeutic target in reducing cancer stemness." (PMID 35406578, 2022). "These differentially expressed RBPs modulated by mTOR signaling suggest a comprehensive role of mTOR in the transcriptome by post-transcriptional regulatory pathways that could be important for cancer progression." (PMID 36293270, 2022). "The AKT and mTOR pathways are downregulated in cancer cells, inducing autophagy." (PMID 36555406, 2022). "Proteins including progesterone receptor (PR), epidermal growth factor receptor (EGFR), mechanistic target of rapamycin (mTOR), p53R2, cytotoxic T-lymphocyte–associated antigen 4 (CTLA-4), cyclin dependent kinase-(CDK8), etc. can be used as therapeutic targets to stop cancer from progressing." (PMID 36235128, 2022). "Akt/mTOR pathway regulates cell growth and metastasis of cancer cells, including ESCC cells." (PMID 35315581, 2022). "Overcoming resistance to mTOR inhibitors and using metabolic derangements of cancer cells for active targeting of the mTOR pathway may be of value." (PMID 35326708, 2022). "In addition to DNA, PI3K/mTOR signaling pathways, which are accepted as the main regulators for cancer, are also important in the pharmacological targeting of anticancer drugs." (PMID 35335262, 2022). "Aspirin also targets metabolic pathways via activation of AMPK and inhibition of mTOR; notably, these are also important in the anti-cancer activities of metformin, and there is some interest in exploring the potential synergy of the two drugs in cancer treatment." (PMID 35406393, 2022). "Moreover, abnormal activation of the Wnt/β-catenin and AKT/mTOR pathways is frequently observed in various cancers, including colorectal cancer; therefore, the components of these pathways constitute attractive therapeutic targets." (PMID 35530256, 2022). "Furthermore, the PI3K/Akt/mTOR pathways are regarded as promising targets for cancer therapy due to their important role in the process of cell proliferation, growth, survival, and mobility." (PMID 36287985, 2022). "In addition, combining mTOR inhibitor with target therapy and standard chemotherapeutic drugs have yielded superior clinical outcome than individual therapy in several cancer types." (PMID 35655775, 2022). "The AKT/mTOR pathway is therefore highly activated in numerous cancers." (PMID 36188542, 2022). "The mTOR pathway necessary for cancer development has two essential components: mTORC1 and mTORC2." (PMID 36267272, 2022). "Furthermore, GSEA showed that the genes in the high-risk group were significantly enriched in cancer-related pathways, such as “MAPK signaling pathway”, “mTOR signaling pathway”, “VEGF signaling pathway” and so on." (PMID 35769257, 2022). "Amygdalin has been demonstrated to block the Akt-mTOR pathway, which may lead to a decrease in cancer cell metastasis by preventing cancer cells from adhering to one another." (PMID 36291723, 2022). "In vivo, mTOR inhibitors, notably rapalogs, cause cancer cell death, but not at dosages that decrease cell proliferation in culture." (PMID 36293326, 2022). "The highly conserved PI3K/Akt/mTOR signaling pathway is commonly deregulated in cancer." (PMID 36497226, 2022). "Many studies indicated the PI3K/Akt/mTOR pathway regulates cancer cell apoptosis." (PMID 35606807, 2022).
cancer (continued). "GSEA analysis revealed that G2E3 might be enriched in the E2F, PI3K/AKT/mTOR signaling, DNA repair pathways, and other cancer-related signaling pathways." (PMID 36517818, 2022). "Rapamycin, a selective inhibitor of the (mTOR), is a promising cancer therapeutic option." (PMID 36293326, 2022). "Constitutive upregulated mTOR activity leads to cancer cells with unregulated growth and inhibition to autophagy thus conferring them a survival advantage and as such targeting mTOR activity has been a therapeutic approach of great interest in a number of tumor types." (PMID 36046843, 2022). "Further investigation of USP30’s function in regulating AKT/mTOR signaling may offer new therapeutic approaches in cancer treatment." (PMID 35250566, 2022). "As a result, the activation of mTOR has been documented in up to 80% of human cancers." (PMID 35955931, 2022). "mTOR complex is recently depicted as a nutrient sensor in the metabolism of cancer." (PMID 36311939, 2022). "Similarly, the combination of baicalein and docetaxel, and glioma-associated oncogene antagonist 61, also appeared to induce anti-cancer effects in 8505C cells through the suppression of the mTOR pathway." (PMID 36551653, 2022). "mTOR is a serine/threonine kinase involved in the deregulated PI3K/Akt pathway in most cancers." (PMID 35884563, 2022). "In cancer cells, mTOR promotes metastasis, growth of tumor cells, and invasion of healthy tissues." (PMID 35795855, 2022). "A study revealed that excessive glucose uptake by tumor cells restricts the anti-cancer activity of tumor-infiltrating T cells, which leads to increased glycolytic capacity, dampened the mechanistic target of rapamycin kinase (mTOR) activity, and allows tumor progression." (PMID 36072431, 2022). "Similarly, melanoregulin (MREG) downregulates the phosphatidylinositol 3 kinase (PI3K)/Akt-mTOR signaling pathway and simultaneously inhibits the invasion and proliferation of cancer cells." (PMID 36761693, 2022). "Several mTOR inhibitors have reached various stages of clinical trials, but only temsirolimus and everolimus have been approved by the Food and Drug Administration for clinical use in the treatment of cancer patients." (PMID 35883111, 2022). "Interestingly, MTOR is not significantly coordinately expressed with any of its MTORC1 and MTORC2 alleged partners in the nodules “Q”, “M”, “B” and “C”, indicating major remodeling of the mTOR signaling in these cancer clones." (PMID 35723406, 2022). "Investigations into the mechanism of action of rapamycin, a macrolide inhibitor of mTOR generated by bacteria with a wide range of clinical applications such as an antifungal, immunosuppressant, and anti-cancer medication, have yielded several insights into mTOR signaling." (PMID 35370701, 2022). "It has been reported that mTOR is aberrantly overactivated in more than 70% of cancers." (PMID 35579750, 2022). "SESN2 is reported to activate autophagy via the AMPK/mTOR pathway in cancers." (PMID 36588732, 2022). "mTOR signaling activity, specifically pS6 accumulates in multiple HPV-associated cancers." (PMID 35938153, 2022). "The inhibition of mTOR also increases the drug sensitivity of cancer cells." (PMID 36293209, 2022). "This metabolism heterogeneity makes cancer metabolism difficult to target because it can switch at any time using PI3K/AKT/mTOR or another unknown pathway." (PMID 35392088, 2022). "Thus, to investigate the anti-cancer effect of pre-miR-199a/Rheb/mTOR axis in NSCLC, miR-199a-3p and miR-199a-5p have the potential to become an early diagnostic marker or therapeutic target for NSCLC." (PMID 35844793, 2022). "Importantly, IL-6 is a facilitator of cancer anorexia and the primary inducer of cancer anemia, and both states inhibit the mTOR axis, resulting in a vicious loop that accelerates muscle wasting." (PMID 35159388, 2022). "Interestingly, dysregulated PI3K-Akt-mTOR signaling in cancer has been increasingly utilized for developing targeted therapies." (PMID 36267966, 2022).